GABRB1 (gamma-aminobutyric acid type A receptor subunit beta1)
Description:
Beta subunit of the heteropentameric ligand-gated chloride channel gated by gamma-aminobutyric acid (GABA), a major inhibitory neurotransmitter in the brain. GABA-gated chloride channels, also named GABA(A) receptors (GABAAR), consist of five subunits arranged around a central pore and contain one or two GABA active binding sites located at the alpha and beta subunit interfaces, depending on subunit composition (By similarity). When activated by GABA, GABAARs selectively allow the flow of chloride anions across the cell membrane down their electrochemical gradient. Chloride influx into the postsynaptic neuron following GABAAR opening decreases the neuron ability to generate a new action potential, thereby reducing nerve transmission. Beta-containing GABAARs can simultaneously bind GABA and histamine where histamine binds at the interface of two neighboring beta subunits, which may be involved in the regulation of sleep and wakefulness (By similarity).
Synonyms: DEE45; EIEE45
Tractability: Small molecule: an approved drug acts on it; a structure with a bound ligand is known; a high-quality ligand is known; it belongs to a druggable protein family. Antibody: UniProt places it where antibodies can reach, with high confidence; its Gene Ontology location is reachable by antibodies, with high confidence; UniProt predicts a signal peptide or a membrane-spanning region. PROTAC: ubiquitination databases record sites on it; its protein half-life has been measured; a small molecule that binds it is known.
Target class: Ion channel; GABA-A receptor; Ligand-gated ion channel
Gene: Protein-coding gene on chromosome 4 (46,993,723 to 47,426,447, forward strand). Ensembl gene ENSG00000163288.
Subcellular location: Postsynaptic cell membrane; Cell membrane
Pathways (Reactome):
Neuronal System: GABA receptor activation
Signal Transduction: Signaling by ERBB4
Gene Ontology:
Molecular function: GABA-A receptor activity; GABA-gated chloride ion channel activity; ligand-gated monoatomic ion channel activity involved in regulation of presynaptic membrane potential; ligand-gated monoatomic ion channel activity; extracellular ligand-gated monoatomic ion channel activity; G protein-coupled neurotransmitter receptor activity; GABA receptor binding; monoatomic anion channel activity; monoatomic ion channel activity; transmembrane signaling receptor activity; transmitter-gated monoatomic ion channel activity involved in regulation of postsynaptic membrane potential
Biological process: chloride transmembrane transport; gamma-aminobutyric acid signaling pathway; cellular response to histamine; extrasynaptic signaling via GABA; monoatomic ion transport; negative regulation of synaptic transmission, GABAergic; signal transduction; synaptic transmission, GABAergic; central nervous system neuron development; G protein-coupled receptor signaling pathway; monoatomic ion transmembrane transport; ovulation cycle; regulation of postsynaptic membrane potential; regulation of presynaptic membrane potential; response to progesterone; response to toxic substance
Cellular component: GABA-A receptor complex; plasma membrane; GABA-ergic synapse; postsynaptic membrane; dendrite; membrane; nuclear envelope; postsynaptic specialization membrane; presynaptic active zone membrane; receptor complex; Schaffer collateral - CA1 synapse
Genetic constraint (gnomAD): Loss-of-function variants: 17 observed, 45.15 expected, observed/expected ratio (o/e) 0.38, 90% interval 0.26 to 0.56. The upper end of that interval is the gene's LOEUF score, 0.56, which puts it in group 2 of 6, group 1 being the genes least tolerant of losing a copy. Missense variants: 376 observed, 573.46 expected, observed/expected ratio (o/e) 0.66, 90% interval 0.6 to 0.71. Synonymous variants: 226 observed, 213.36 expected, observed/expected ratio (o/e) 1.06, 90% interval 0.95 to 1.18.
Gene-disease validity (ClinGen):
ClinGen rates the evidence that GABRB1 causes each of these diseases.
genetic developmental and epileptic encephalopathy (autosomal dominant): Limited. A complex neurodevelopmental disorder characterized by a range of developmental delays and epileptic encephalopathy phenotypes.
Homologues: Orthologues: chimpanzee GABRB1 (100% identical), macaque GABRB1 (99% identical), pig GABRB1 (99% identical), rat Gabrb1 (98% identical), mouse Gabrb1 (98% identical), guinea pig GABRB1 (87% identical). Paralogues in human: GABRB2 (79% identical), GABRB3 (76% identical), GABRQ (44% identical), GABRR2 (38% identical), GABRD (38% identical), GABRR1 (37% identical), GABRP (36% identical), GABRR3 (36% identical), GLRA2 (35% identical), GABRA4 (34% identical), GABRG2 (34% identical), GLRA1 (34% identical), and 33 more.
Diseases named in the same sentence as GABRB1 in open-access papers:
GABRB1 is named in the same sentence as 42 diseases in open-access papers, as found by Europe PMC text mining. Sharing a sentence is not in itself a finding about the gene and the disease. The quoted sentences say what the papers report.
alcoholism (8 papers, 2005 to 2024). "Human genetic association studies have demonstrated that the GABRB1 gene is associated with bipolar disorder, schizophrenia, alcohol dependence, and alterations of brain function." (PMID 39334212, 2024). "The highest peak for LODPAL is at the GABRB1 gene that has been identified previously as being linked to alcoholism." (PMID 16451603, 2005). "The marker GABRB1 at 51.4 cM on chromosome 4 has already been identified before to be associated with alcoholism." (PMID 16451575, 2005). "In the present study, we hypothesized that the GABRB1 genetically-associated increased risk for developing alcoholism may be associated with impaired behavioral control and altered sensitivity to reward, as a consequence of altered brain function." (PMID 28261068, 2017). "In support of Gabra2-Gabrb1 covariance in expression, a GABRA2 risk variant for alcohol dependence leading to reduced expression of GABRA2 positively correlated with expression of GABRB1, GABRG1 and GABRA4 in human iPSCs." (PMID 34677900, 2021). "Among these, a number of human studies have suggested an association between GABRB1, the gene encoding GABAA receptor β1 subunits, with Alcohol dependence (AD), both on its own and comorbid with other substance dependence and psychiatric illnesses." (PMID 28261068, 2017). "GABRB1 (4p12) and GABBR2 (9q22.33, 143 kb upstream of rs73655199) are major neurotransmitters in the vertebrate brain, representing ligand-gated ion channels and have been shown to associate with alcohol dependence." (PMID 29912962, 2018). "However, there has been no equivalent indication of linkage to GABRB1 with a categorical alcoholism phenotype in the literature, while our results indicate a 26% of linkage to alcoholism." (PMID 16451579, 2005).
autism (8 papers, 2018 to 2025). Persistent deficits in social interaction and communication and interaction as well as a markedly restricted repertoire of activity and interest as well as repetitive patterns of behavior. "Hub genes of the turquoise module included one GABA receptor encoding genes such as Gabrb1, one glutamate receptor gene (Grid2) and genes tightly associated with synaptic development and autism (Nrxn1, Lrfn5, Plcb1, Erc2, Frmpd4, Tanc2, Ctnnd2, Dmd)." (PMID 34021132, 2021). "GABRA4 was also found to increase autism risk through interaction with GABRB1, indicating a complex gene–gene interaction in GABA receptor subunit genes involved in the ethology of autism." (PMID 35198562, 2021). "Association studies also suggest that GABRA4 and GABRB1 contribute to the susceptibility for autism." (PMID 32033586, 2020). "Further support for an association of GABRB1 with autism is evidenced by a decrease in β1 subunit levels in the brains of autistic subjects." (PMID 30186109, 2018). "A family-based association and linkage disequilibrium study has found a genetic interaction between GABRA4 and GABRB1 in the etiology of autism." (PMID 32033586, 2020). "GABRB1 protein levels were demonstrated to be altered specifically in the superior frontal cortex of subjects with autism, and in addictive behaviors, apparently, because it plays a role in the excitability of brain regions important in controlling reward-related behaviors." (PMID 32120974, 2020). "Focusing on just the top 1% in the two validation datasets, given their high correlation, we identified several other genes that have been implicated in autism and synaptic transmission including GABRA3, GABRA5 and GABRB1, all of which encode subunits of the GABA receptor." (PMID 29483624, 2019). "As GABRB1 and GABRA4 lie within the same GABAR gene cluster and their promoters are head-to-head, it is interesting to note that the association of GABRA4 with autism risk increases with a GABRB1 interaction, suggesting that these genes may be coordinately regulated." (PMID 30186109, 2018).
epilepsy (7 papers, 2016 to 2026). A brain disorder characterized by episodes of abnormally increased neuronal discharge resulting in transient episodes of sensory or motor neurological dysfunction, or psychic dysfunction. "Among the top ten hyper- and top ten hypo-methylated genes, a subset (i.e., GABRB1, LC34A2, CLCN6, CLCA4, CYP3A43, CYP3A4, CYP2C9) has been related to epilepsy in epidemiological, pathophysiological or clinical context (to be discussed further)." (PMID 28276448, 2017). "We found that variants in the epilepsy-associated genes GABRA1, GABRB3 and GABRG2 were mainly present in the ESP variants, but the GEC cohort contained epilepsy-associated GABRA6, GABRB1, and GABRB2 and non-epilepsy- associated GABRA4, GABRA5, and GABRG3 genes." (PMID 27622563, 2016).
schizophrenia (6 papers, 2017 to 2024). A major psychotic disorder characterized by abnormalities in the perception or expression of reality. "Particularly in schizophrenia, a significant association of GABRB1 has been identified by genome-wide association studies that were coupled to a protein-interaction-network-based analysis." (PMID 30186109, 2018). "The GABRB1 gene had also been associated with many neuropsychological diseases, such as schizophrenia, major depression, bipolar disorder, and Alzheimer’s disease." (PMID 28558704, 2017). "GABRB1 expression is also reduced in the lateral cerebella of subjects with bipolar disorder, major depression, and schizophrenia compared to healthy subjects." (PMID 30186109, 2018). "Both GABRA4 and GABRB1 mRNA and protein were found to alter their expression in the parietal and frontal cortex and cerebellum of patients with ASD and in the lateral cerebellum of patients with schizophrenia and with affective disorders." (PMID 29179725, 2017).
Anxiety (4 papers, 2021 to 2026). Intense feelings of nervousness, tension, or panic often arise in response to interpersonal stresses. "Treatment with probiotic BaSC06 is probably linked to reduced fear behaviors and the promotion of the expression of the anti-anxiety genes GABA and GABRB1." (PMID 38891594, 2024).
bipolar disorder (4 papers, 2017 to 2025). A disorder of the brain that causes unusual shifts in mood, energy, activity levels and the ability to carry out day-to-day tasks. "Previous studies have reported that GABRB1 is associated with bipolar disorder, and our data also revealed the notable increases of the inhibitory postsynaptic scaffolding protein Gephyrin and inhibitory receptor of GABRB1 in the Kif15-/- mice." (PMID 40892874, 2025).
breast carcinoma (4 papers, 2023 to 2025). "Furthermore, OPRK1 has been implicated in facilitating the migration of breast cancer cells, while the low expression of GABRB1 correlated with a poor prognosis in colon adenocarcinoma." (PMID 37873862, 2023).
colon adenocarcinoma (2 papers, 2023 to 2024). "For example, the expression of GABRB2 and GABRB3 is associated with colon adenocarcinoma occurrence, and a low expression of GABRB1 correlates with patient survival in that cancer type." (PMID 39595908, 2024).
Hypertension (2 papers, 2017 to 2018). The presence of chronic increased pressure in the systemic arterial system. "Two of the genes, CDH13 and GABRB1, have been associated with hypertension in a previous GWAS." (PMID 28642868, 2017).
anterograde amnesia (1 paper, 2025). "This implies that certain GABRB1 mutations impact the possible effects of midazolam—amnesia, sedation, and anterograde amnesia." (PMID 40136457, 2025). "Two SNPs in the GABRB1 gene, rs73247636 (p = 0.001) and rs56278524 (p < 0.001), demonstrated a significant association with sedation and the occurrence of anterograde amnesia." (PMID 40136457, 2025).
benign adult familial myoclonus epilepsy (1 paper, 2023). "The first reported linkage study of FAME (or benign adult familial myoclonus epilepsy) targeted the gene for dentatorubral pallidoluysian atrophy (DRPLA), in which a causative CAG repeat expansion had been discovered, and the GABRB1, GABRB3, and GABRB6 genes." (PMID 37021642, 2023).
dilated cardiomyopathy (1 paper, 2022). Cardiomyopathy which is characterized by dilation and contractile dysfunction of the left and right ventricles. "Second, AQP4, VSNL1, GABRA4, and GABRB1 were still among the hub genes obtained by subgroup analysis, indicating that these genes were strongly associated with dilated cardiomyopathy caused by myocarditis." (PMID 36286305, 2022).
Dravet syndrome (1 paper, 2021). "Recently, GABAA receptor subunit genes (GABRs) encoding α1 (GABRA1), β3 (GABRB3) and γ2 (GABRG2), but not β2 (GABRB2) or β1 (GABRB1), subunits are frequently associated with Dravet syndrome or Dravet syndrome-like phenotype." (PMID 34095830, 2021).
Dyskinesia (1 paper, 2024). A movement disorder which consists of effects including diminished voluntary movements and the presence of involuntary movements. "Furthermore, Guanabenz shows potential in elevating parkin levels to combat neurodegeneration, and Topiramate paired with GABRB1 may help manage levodopa-induced dyskinesia." (PMID 39273521, 2024).
Encephalopathy (1 paper, 2022). Encephalopathy is a term that means brain disease, damage, or malfunction. "Encephalopathy is characteristic of 112 IMDs (19%) that are often classified as developmental and epileptic encephalopathies (DEE) (e.g., early infantile epileptic encephalopathies due to GABRA1, GABRB1, GABRB2 or GABRB3 pathogenic variants)." (PMID 35328062, 2022).
medulloblastoma (1 paper, 2024). A malignant, invasive embryonal neoplasm arising from the cerebellum. "Here, we show the expression of genes encoding β subunits of the GABAA receptor, namely GABRB1, GABRB2, and GABRB3, across the four different molecular subgroups of medulloblastoma (MB), which is the most common malignant pediatric brain tumor." (PMID 39595908, 2024).
methamphetamine dependence (1 paper, 2025). A drug dependence that is a psychological dependency on the regular use of methamphetamine. "The methylation level of CG2 within the GABRB1 gene exhibited remarkable diagnostic significance for methamphetamine dependence (p = 6.47E−11), with an area under the ROC curve (AUC) of 0.902 (95% CI: 0.836–0.969), a sensitivity of 0.85 and a specificity of 0.88." (PMID 41368944, 2025). "The high AUC value (area under the curve) of GABRB1 methylation level indicated that it has excellent diagnostic performance and may be used as a biomarker for methamphetamine dependence." (PMID 41368944, 2025). "Notably, the observed hypomethylation of GABRB1, and KCNQ2, along with the hypermethylation of CES1 and USP7, may underlie the pathophysiology of methamphetamine dependence." (PMID 41368944, 2025).
ovarian carcinoma (1 paper, 2023). A malignant neoplasm originating from the surface ovarian epithelium. "Gene expression levels for OPRK1 and GABRB1 were extremely low in healthy cells and upregulated in ovarian cancer cisplatin-sensitive and -resistant cells." (PMID 37873862, 2023). "For instance, using SPR, we reveal poor interaction between anti-OPKR1-rOPKR1 and anti-GABRB1-rGABRB1, although antibodies still recognise the denatured recombinant proteins by immunoblot as well as the ovarian cancer samples." (PMID 37873862, 2023). "Similarly, 83% of tumours expressed PDCHB10 in more than 75% of ovarian cancer cells, whereas this distribution of staining was observed in 75% of tumours assessed for GABRB1 expression." (PMID 37873862, 2023).
RASopathy (1 paper, 2017). Developmental syndromes caused by germline mutations (or in rare cases by somatic mosaicism) in genes that alter the Ras subfamily and mitogen-activated protein kinases that control signal transduction. "Additional genes listed in SFARIgene adjacent to our top RASopathy social responsiveness QTL results include CNTN5, ESRRB, GABRB1, GNB1L, and ICA1." (PMID 28076348, 2017).
substance dependence (1 paper, 2017). The psychological or physiological need to take a substance in order to experience its effects or to avoid the effects of its absence. "Variations in GABRA2 have been most frequently associated with addictions and related behaviors, but there is also a robust association of GABRB1 with AD comorbid with other substance dependence and psychiatric illnesses." (PMID 28261068, 2017).
temporal lobe epilepsy (1 paper, 2007). A localization-related (focal) form of epilepsy characterized by recurrent seizures that arise from foci within the temporal lobe, most commonly from its mesial aspect. "GABRB1 mRNA is known to be downregulated by persistent GABAA receptor activation and in a model of temporal lobe epilepsy." (PMID 17266762, 2007).
cancer (3 papers, 2024 to 2026). A tumor composed of atypical neoplastic, often pleomorphic cells that invade other tissues. "The association with GABRB1 indicates the significance of amino acid transport and neurotransmission in cancer cell metabolism and survival, highlighting potential new therapeutic avenues." (PMID 39267843, 2024). "The association of SLC23A2 with GABRB1 indicates potential interactions related to amino acid transport and neurotransmission in cancer cells." (PMID 39267843, 2024).
tumours (3 papers, 2023 to 2024). "GABRB1, PCDHB10, and LRP6 also showed that 80% to 90% of the patients exhibited expression of the biomarker in more than 75% of tumour cells." (PMID 37873862, 2023).
infection (1 paper, 2020). The state of being infected such as from the introduction of a foreign agent such as serum, vaccine, antigenic substance or organism. "Other genes we identified are likely subject to strong selection during winter periods of infection, but could also be important year-round (cGMP-PK1, PLA2G7, and GABRB1), given their functions in cellular metabolism." (PMID 32080246, 2020).
GABRB1 also shares sentences with these, for which no sentence is quoted: depression (3 papers); mental disorder (3); developmental and epileptic encephalopathy (2); acute coronary syndrome (1); alcohol abuse (1); Alzheimer disease (1); anxiety disorder (1); dentatorubral-pallidoluysian atrophy (1); epileptic encephalopathies (1); glial tumors (1); idiopathic generalized epilepsy (1); infantile epileptic encephalopathy (1); infarction (1); Insulin resistance (1); myocarditis (1); Rett syndrome (1); Sciatica (1); viral myocarditis (1).